HPRT1 (hypoxanthine phosphoribosyltransferase 1)
Diseases named in the same sentence as HPRT1 in open-access papers (continued):
Sharing a sentence is not in itself a finding about the gene and the disease.
cancer (continued). "However, limitations exist, such as a smaller sample size in immunohistochemistry and the need for larger sample sizes and deeper and more comprehensive pan-cancer HPRT1 analysis may provide insights for future exploration of the role of HPRT1 in cancer." (PMID 38159260, 2024). "Therefore, further research is warranted focusing on the role of HPRT1 as a potential oncogene, which may have important implications for cancer treatment." (PMID 35205603, 2022). "Likewise, HPRT1 expression levels were elevated in individual cancer types derived from different organs compared to its expression aggregated across normal tissues, showing significant elevation in cancers, including those of the kidneys, lung, colon, esophagus, bladder, and breast, amongst others." (PMID 32532008, 2020). "Collectively, our study suggests that HPRT1 should be treated as a biomarker rather than as a housekeeping gene, and its differential expression during cancer could be exploited as a potential diagnostic or therapeutic target." (PMID 32532008, 2020). "The present study explored the GEPIA database to investigate the expression levels and functions of HPRT1 and PYGL in multiple cancer types." (PMID 37371537, 2023). "RALGPS1, NUDT9, NUDT2, and PDE4A were less expressed in cancer cell lines; JUP, ADA, HPRT1, and IMPDH1 were highly expressed in cancer cell lines in CCLE." (PMID 34745385, 2021). "To compare the functional maps with their corresponding protein structures, we highlighted those critical residues identified from PASTMUS on the surface diagram of three cancer drug targets (PSMB5, PLK1, and HPRT1)." (PMID 31842968, 2019). "Expression of HPRT1, Jag2, AURKA, and PGK1 were elevated when compared to normal samples, and HPRT1 and PGK1 showed a stepwise elevation in expression that was significantly related to cancer grade." (PMID 30679932, 2019). "We systematically addressed the existence of a correlation between the expression levels of APRT, HPRT1, XDH in the 60 human cancer cell lines and their pattern of drug sensitivity." (PMID 30104401, 2018). "The potential reference genes GAPDH, HPRT1, and RPLP0 were measured in all samples from NSCLC patients and cancer-free controls." (PMID 24313945, 2013). "We examined, in addition to ACTB and GAPDH, four other reference genes, HPRT1, RPL29, 18S rRNA, and B2M that have been evaluated as reference genes in recent studies for other human cancers." (PMID 20507635, 2010). "Recently, both HPRT1 and TBP were indicated as suitable reference genes for differential expression studies using qRT-PCR in different type of cancers, moreover HPRT1 was recommended as a universal single reference gene for expression analysis in cancer." (PMID 19257903, 2009). "A review on the selection of normalizers for RT-qPCR cancer studies recommended that a combination of PPIA and ACTB, HPRT1 (hypoxanthine phosphoribosyltransferase 1), TBP (TATA-binding protein), or GAPDH, or an appropriate combination of three of these genes, should be employed." (PMID 40943534, 2025). "In addition, the role of genes closely related to HPRT1, such as GMPR2 and phosphoribosyl transferase domain containing (PRTFDC1), in pan-cancer needs to be addressed." (PMID 38159260, 2024). "HPRT1 has been shown to be involved in the pathogenesis of various human cancers, but its mechanism of action has not been reported in ESCC." (PMID 38485739, 2024). "Overall, these findings suggested that HPRT1 and PYGL might play important roles in cancer development and prognosis." (PMID 37371537, 2023). "The most stable expressed gene in MM cancer tissues was ACTB, with a lower average between mean SD and mean Ct (1.17 for ACTB; 1.22 for HPRT1; 1.62 for TFRC), while in CSCC cancer tissues it was TFRC (1.00 for TFRC; 1.13 for HPRT1; 1.45 for ACTB)." (PMID 34940125, 2021). "The expression of HPRT1 was elevated when aggregated across cancer types in comparison to its expression aggregated across normal tissues." (PMID 32532008, 2020).
cancer (continued). "With the HPRT1 as the reference, higher expressions of these genes were noticed in at least some of the cancer tissues." (PMID 23282184, 2012). "Finally, coherent and high gene expression of SLC29A2, TK1 and HPRT1 was observed in the three cell lines considered, according to CCLE (Cancer Cell Line Encyclopedia), which enable alternative salvage pathways for purine and pyrimidine synthesis through thymidine and hypoxanthine, respectively." (PMID 35286311, 2022). "Especially in the case of both HPRT1 and AURKA, it may be beneficial to develop therapies to reduce their expression, thereby determining whether these genes play a critical role in cancer survival and proliferation as they show significant impact on overall patient survival." (PMID 30679932, 2019). "To investigate HPRT1 expression in oral tissues, we collected 6 pairs of fresh primary OSCC tissues and adjacent non-neoplastic tissues from patients at our cancer center." (PMID 35205603, 2022).
infection (17 papers, 2010 to 2024). The state of being infected such as from the introduction of a foreign agent such as serum, vaccine, antigenic substance or organism. "To corroborate this finding, we used CRISPR/Cas9 genome editing to silence expression of HPRT1 in 293T cells prior to infection with HCoV-OC43 and treatment with 6-TG or vehicle control." (PMID 36121863, 2022). "We determined the mRNA expression levels of several housekeeping genes (GAPDH, B2M, HPRT1) to examine the effect of infection with H6R28LEP on PBMCs." (PMID 23409116, 2013). "Importantly, both PEX3 and HPRT1 KD blocked HCMV at early stages of infection as the expression of early-proteins IE2 and UL44 was reduced." (PMID 26599541, 2015). "This is the first report exploring reference gene expression during a NNV infection in halibut, and amongst the genes tested especially RPL7 was shown to be a good candidate, but also EF1A1 and HPRT1." (PMID 20459764, 2010).
neurological disorders (12 papers, 2009 to 2025). "Intriguingly, mutations in Hprt1 gene cause Lesch–Nyhan syndrome (LNS), which is a rare neurologic disorder exhibiting accumulation of uric acid caused by a defect in nucleic acid metabolisms." (PMID 32868309, 2020). "Since miR-301b-3p expression is up-regulated in neurologic disorders, we selected miR-301b-3p as the research biomarker, to test the hypothesis that H19 might regulate HPRT1 expression by “sponging” miR-301b-3p, thus participating in the 6-OHDA-induced dopaminergic neuron loss." (PMID 32434961, 2020).
blood cancer (1 paper, 2023). "Among them, HPRT1, TSC22D1, and COX16 have significantly correlated dependence profiles (p < 0.05) with PRDM15 in lymphocyte or blood cancer cell lines from these pathways." (PMID 36674842, 2023).
heart disease (1 paper, 2016). "HPRT1 was expressed less stably than other housekeeping genes in a publication evaluating housekeeping genes for the study of heart disease." (PMID 27625650, 2016).
respiratory diseases (1 paper, 2012). "Since in the most cases, Gram-negative and Gram-positive bacteria are observed together in respiratory diseases, HPRT1, YWHAZ and SDHA might be an appropriate set of reference genes for the gene expression normalization in AM studies." (PMID 22340302, 2012).
HPRT1 also shares sentences with these, for which no sentence is quoted: genetic diseases (7 papers); lymphoma (7); Alzheimer disease (6); Intellectual disability (6); cognitive deficits (5); kidney stones (5); acute renal failure (4); colon adenocarcinoma (4); acute myeloid leukemia (3); embryonic carcinoma (3); metabolic disorder (3); myeloma (3); ovarian carcinoma (3); autism (2); cerebral palsy (2); Choreoathetosis (2); Duchenne muscular dystrophy (2); fragile X syndrome (2); Glutaric Aciduria type 1 (2); hepatocellular carcinoma (2); HPRT deficiency (2); Hunter syndrome (2); inflammatory bowel disease (2); microcephaly (2); neurodegenerative disease (2); neurodevelopmental disorder (2); Obesity (2); pancreatic cancer (2); Parkinson's (2); retinoblastoma (2).
A further 98 diseases each share a sentence with HPRT1 in 2 papers or fewer.